SIRT4 (sirtuin 4)
Diseases named in the same sentence as SIRT4 in open-access papers (continued):
Sharing a sentence is not in itself a finding about the gene and the disease.
cardiac hypertrophy (22 papers, 2016 to 2025). "In the cardiovascular system, Sirt4 deficiency has been shown to confer protection against angiotensin II‐induced cardiac hypertrophy and fibrosis." (PMID 40842073, 2025). "Strictly, loss of Sirt4 protected the mice from Ang II-induced cardiac hypertrophy, whereas cardiac overexpression of Sirt4 accelerated cardiac maladaptation in response to Ang II treatment." (PMID 35118147, 2021). "MiR-497, a potential therapeutic substance, has been found to modulate cardiac hypertrophy by targeting Sirt4." (PMID 41567643, 2025). "By raising ROS levels, Sirt4-mediated hypertrophic response was inhibited through the development, fibrosis, and cardiac dysfunction, pointing to a possible involvement for Sirt4 in pathological cardiac hypertrophy." (PMID 41567643, 2025). "SIRT2 and SIRT4 have been shown to have deleterious effects on ischemia–reperfusion injury and cardiac hypertrophy, respectively." (PMID 41276460, 2025). "An in vivo study showed that SIRT4 exacerbates Ang II-induced cardiac hypertrophy by overexpressing and inhibiting MnSOD activity, providing new directions and targets for treating cardiac hypertrophy." (PMID 39062982, 2024). "By inhibiting Sirt4 in mitochondria, ROS production can be reduced, thereby alleviating pathological cardiac hypertrophy and fibrosis." (PMID 39553724, 2024). "A recent study demonstrated that the increased expression of miR-497 ameliorated cardiac hypertrophy in vitro and in vivo via targeting sirtuin 4 (Sirt4)." (PMID 33817315, 2021). "The mitochondrial SIRT3 and SIRT5 were cardiac protective factors that repress aging and pathological cardiac hypertrophy, whereas SIRT4 was reported as the only member as a pro-hypertrophic member." (PMID 33611744, 2021). "Sirt4, a sirtuin mainly present in mitochondria, plays an essential role in the progression of cardiac hypertrophy." (PMID 35118147, 2021). "A previous study reported that Sirt4 can promote the cardiac hypertrophy by up-regulating the reactive oxygen species (ROS) levels in Ang II-induced hypertrophic cardiomyocytes." (PMID 27992564, 2016). "We offered further proof for the first time that the overexpression of miR-497 significantly suppressed cardiac hypertrophy by inhibiting the expression of Sirt4." (PMID 27992564, 2016). "Mechanistically, mitochondria-targeted antioxidant treatment prevented the aggravation of cardiac hypertrophy in SIRT4-overexpressing mice, suggesting increased mitochondrial oxidative stress as the cause." (PMID 27790619, 2016). "For the first time, we provide a convictive evidence that miRNA-497 is negatively correlated to Sirt4 and play a key role in suppressing cardiac hypertrophy by targeting the 3’UTR of Sirt4." (PMID 27992564, 2016). "It is noteworthy that in a study of angiotensin II (Ang II)-induced cardiac hypertrophy in mice, it was demonstrated that SIRT4 inhibited the binding of MnSOD to SIRT3, resulting in increased MnSOD acetylation and elevated ROS accumulation upon Ang II stimulation." (PMID 37998340, 2023). "In addition, SIRT2, SIRT5, and SIRT7 have protective effects on cardiac hypertrophy, while SIRT4 appears to have the opposite effect." (PMID 36581622, 2022). "This is a key mechanism in the regulation of not only cardiac hypertrophy but also blood pressure and electrolyte balance, which may indicate an important role of SIRT4 in the pathogenesis of CVD." (PMID 34685718, 2021). "A previous study has shown that sirtuin 4 boosted the hypertrophic growth of cardiomyocytes and the generation of myocardial fibrosis by elevating ROS accumulation in a mouse model of pathological cardiac hypertrophy." (PMID 34518516, 2021). "In addition, SIRT4 knockout mice showed significantly greater heart ROS production compared to WT during cardiac hypertrophy, which is an unfavorable factor in the development of cardiac disorders." (PMID 34685718, 2021).
cardiac hypertrophy (continued). "However, experiments in mice investigating angiotensin II (Ang II)-induced cardiac hypertrophy revealed that overexpression of Sirt4 increased ROS, while Sirt4 KO increased and decreased ROS in the heart and mitochondria, respectively." (PMID 34439446, 2021). "In our future work, we will focus on whether miR-497 regulates ROS by targeting Sirt4 in cardiac hypertrophy." (PMID 27992564, 2016). "Taking together, our study indicates that miR-497 modulates cardiac hypertrophy by targeting Sirt4 and may serve as a potential therapeutic substance in the course." (PMID 27992564, 2016). "In addition, we also confirmed that miR-497 suppress cardiac hypertrophy by targeting 3’UTR of Sirt4 during cardiac hypertrophy." (PMID 27992564, 2016). "In contrast, SIRT4 might exacerbate cardiac hypertrophy and fibrosis." (PMID 36581622, 2022). "Of note, SIRT4 might aggravate cardiac hypertrophy and fibrosis." (PMID 36581622, 2022). "Through these and likely other enzymatic and non-enzymatic activities, Sirt4 closely controls various metabolic events, and its dysregulation is linked to various aging-related disorders, including type 2 diabetes, cardiac hypertrophy, non-alcoholic fatty liver disease, obesity, and cancer." (PMID 32373514, 2020). "Interestingly, it has been recently demonstrated that SIRT4 inhibits SIRT3-mediated MnSOD deacetylation, leading to an increase in ROS levels during cardiac hypertrophy." (PMID 37998340, 2023). "Furthermore, by affecting the miR-93-5p/SIRT4 pathway, the lncRNA MALAT1 may reduce cardiac hypertrophy." (PMID 41567643, 2025). "This action, which seems non-enzymatic because the catalytically inactive mutant of Sirt4 H161Y is also able to block the Sirt3–MnSOD interaction, induces an increase of ROS levels and oxidative stress in the mitochondria of heart muscle cells and promotes cardiac hypertrophy." (PMID 32373514, 2020).
colorectal cancer (15 papers, 2016 to 2025). A primary or metastatic malignant neoplasm that affects the colon or rectum. "Further, a decrease in SIRT4 expression is closely associated with the progression and recurrence of colorectal cancer." (PMID 30761005, 2019). "In colorectal cancer, SIRT4 suppresses malignant phenotypes by activating glutaminase and inhibiting the AKT/GSK3β/CyclinD1 pathway." (PMID 40710366, 2025). "SIRT4 expression is downregulated in most tumors, including gastric cancer, colorectal cancer, hepatocellular cancer and thyroid cancers." (PMID 37301821, 2023). "Several studies have reported that SIRT4 has a low expression in tumors, such as colorectal cancer, and clear cell renal cell carcinoma." (PMID 35847357, 2022). "It has been reported that SIRT4 is decreased in colorectal cancer (CRC) and exerts inhibitory effects by targeting GLS-mediated AKT/GS3β/cyclin D1." (PMID 35847357, 2022). "In colorectal cancer, decreased SIRT4 expression has been correlated with progression and increased invasive potential of cancer cells, and in both colorectal and gastric cancers lower SIRT4 expression is associated with poor prognosis." (PMID 32292719, 2020). "This is consistent with a previous study showing that SIRT4 knockout decreases chemosensitivity to fluorouracil in colorectal cancer cells." (PMID 31573734, 2019). "In colorectal cancer cells, SIRT4 suppresses migration and invasion while upregulating E-cadherin expression." (PMID 31817470, 2019). "In colorectal cancer, SIRT4 overexpression was shown to suppress malignancy by blocking cancer cell proliferation via association with E-cadherin." (PMID 30761005, 2019). "The suppressive role of SIRT4 is also mediated by inhibiting glutamine metabolism in colorectal cancer." (PMID 30666234, 2018). "SIRT4 expression is often dysregulated in disease states; for example, it is upregulated in Alzheimer’s disease, promoting neuronal apoptosis, while decreased expression is observed in colorectal cancer, highlighting its tumor-suppressive role." (PMID 40710366, 2025). "One of the specific studies on CRC proposed that the specific regulatory mechanism of metabolism by microbiota may be the inhibition of glucose metabolism in colorectal cancer cells through the GPR109a-AKT or SIRT4/HIF-1α signaling pathways." (PMID 40927725, 2025). "SIRT4 downregulation in colorectal cancer (CRC) suggests its tumor-suppressive role." (PMID 38773972, 2024). "For example, SIRT4 promotes the progression of colorectal cancer." (PMID 37301821, 2023). "SIRT4 was also reported as a tumor suppressor in colorectal cancer." (PMID 35217651, 2022). "However, SIRT4 silencing prevents the apoptosis of human colorectal cancer cells in response to 5-FU." (PMID 31817470, 2019). "Furthermore, SIRT4 was found to be overexpressed in colorectal cancer cell lines and to increase E-cadherin expression, which resulted in the suppression of cell proliferation and invasion." (PMID 30666234, 2018). "During the development of colorectal cancer invasion, SIRT4 expression was decreased." (PMID 30666234, 2018). "Recent studies reported that SIRT4 seems to have a tumor-suppressive function and may serve as a novel therapeutic target in colorectal cancer." (PMID 29270804, 2016). "Moreover, SIRT4 could enhance the sensitivity of colorectal cancer cells to the chemical drug 5-fluorouracil by inhibiting the cell cycle, thus showing the antiproliferative effect of SIRT4 overexpression." (PMID 30666234, 2018). "Unlike SIRT2 and SIRT4, in the colorectal cancer, SIRT1 was reported to participate in the tumorigenesis, and its expression is positively correlated with the cancer progression in clinic." (PMID 35217651, 2022).
hepatocellular carcinoma (13 papers, 2019 to 2025). A malignant tumor that arises from hepatocytes. "Collectively, these data indicate that MAT2A ADP ribosylation is frequently downregulated in HCC tumors that is associated with high c-Myc but with low SIRT4 protein level, which may be potential biomarkers for hepatocellular cancer diagnosis." (PMID 36371321, 2022). "In contrast, in hepatocellular carcinoma, overexpression of SIRT4 increased the survival of hepatocellular carcinoma cells under stressful conditions such as radiation." (PMID 37301821, 2023). "SIRT4 is aberrantly expressed in colorectal, breast, prostate, and hepatocellular carcinomas and plays an essential role in tumor cell proliferation, differentiation, apoptosis, genomic stability, energy metabolism, DNA damage, and stress response." (PMID 40625712, 2023). "For example, SIRT4 was found to be upregulated in esophageal cancer, and overexpression of SIRT4 increased the clonogenic ability of hepatocellular carcinoma HepG2 cells in response to radiation." (PMID 37301821, 2023). "HBx-mediated SIRT4 suppression is related to an increase in cell cycle progression and the inhibition of apoptosis in hepatoma cells." (PMID 34708060, 2021). "In hepatocellular carcinoma patients, the silencing of SIRT4 in TAMs significantly modulates the alternating activation of macrophages to promote the development of hepatocellular carcinoma." (PMID 34284780, 2021). "SIRT2 and SIRT4, on the other hand, are considered tumor suppressor, downregulated in glioma and hepatocellular carcinoma (SIRT2), and bladder, gastric and lung cancer (SIRT4), among others." (PMID 32344886, 2020). "A deficiency in SIRT4 facilitates liver tumor development and lung metastasis in mice with xenografts and Sirt4 knockout (Sirt4-/-) by promoting colony formation and migration and enhancing the sphere formation of hepatocellular cancer cells." (PMID 31817470, 2019). "This is a study to report a relationship between SIRT4 expression and prognosis in hepatocellular carcinoma." (PMID 31744516, 2019). "HBx suppresses the expression level of SIRT3 and SIRT4 in hepatoma cells." (PMID 34708060, 2021). "It was found that the glycolysis was decreased in overexpressing SIRT4 hepatocellular carcinoma (HCC) cell lines." (PMID 36925927, 2023). "Nonetheless, SIRT4 may also play a tumor promoting role since its activity in cancer cells is protective against endoplasmic reticulum (ER) stress and DNA damage, thus facilitating cancer cell survival and proliferation, as shown in the case of hepatocellular carcinoma (HCC) HepG2 cell line." (PMID 39215785, 2025). "SIRT4 is well-known as a tumor suppressor by controlling several metabolic pathways, although it is highly expressed in certain cancers including hepatocellular carcinoma (HCC)." (PMID 40384857, 2025). "A recent study found that SIRT4 can inhibit methionine metabolism via MAT2A methylation, inhibiting hepatocellular carcinoma progression." (PMID 40625712, 2023). "The SET8/KLF4 complex formation negatively affects the transcriptional activation of SIRT4 by KLF4, thus promoting the proliferation-favorable Warburg effect of hepatocellular carcinoma cells." (PMID 37835497, 2023). "Associations of SIRT3 and SIRT4 were in agreement with earlier reports about their effects on tumour suppression and on improved patient outcomes in hepatocellular carcinoma, and they are consistent with associations of higher SIRT3 expression levels with drug sensitivity in HCC cell lines." (PMID 38369747, 2024).
pancreatic cancer (13 papers, 2020 to 2026). "SIRT4’s role in inhibiting aerobic glycolysis, a hallmark of cancer metabolism, further supports its therapeutic potential in pancreatic cancer." (PMID 39682281, 2024). "Here, we reveal that the voltage‐gated calcium channel subunit α2δ1‐mediated calcium signaling can upregulate the expression of SIRT4, which is highly expressed in α2δ1‐positive pancreatic tumor‐initiating cells (TICs)." (PMID 40298941, 2025). "Therapeutic interventions like Entinostat, which upregulate SIRT4, offer promising strategies to curb pancreatic cancer progression." (PMID 39682281, 2024). "Although reports exploring the role of SIRT4 (SIRT4) in pancreatic cancer are limited, emerging evidence suggests that this mitochondrial protein plays a pivotal role in regulating metabolic processes in pancreatic β-cells and PDAC." (PMID 39682281, 2024). "In pancreatic cancer, SIRT4 assumes a tumor-suppressive role by modulating autophagy, a key process involved in cancer cell survival and growth." (PMID 39682281, 2024). "SIRT4 plays a crucial role in metabolic regulation by inhibiting aerobic glycolysis and promoting autophagy, thus suppressing pancreatic cancer growth." (PMID 39682281, 2024). "mRNA levels of SIRT4, which can act as a tumor suppressor in pancreatic cancer, are upregulated in CM03-treated cells and are unaffected by SAHA." (PMID 33227941, 2020). "UHRF1 drives aerobic glycolysis and proliferation via inhibiting SIRT4 in pancreatic cancer." (PMID 39709438, 2024). "Moreover, UHRF1 promotes cell proliferation through the suppression of SIRT4 in pancreatic cancer." (PMID 35847357, 2022). "Hence, whether SIRT4 exhibits tumor suppressive functions to negatively regulate glutamine metabolism by inhibiting GLUD in pancreatic cancer requires more research." (PMID 33117704, 2020). "For instance, SIRT1 and SIRT7 were reported to promote pancreatic cancer progression, while SIRT2, SIRT4, SIRT5, and SIRT6 seem to play a tumor suppressor role." (PMID 41391757, 2025). "Recently, SIRT4 has been demonstrated to inhibit PDAC cell proliferation and serves as a negative regulator of aerobic glycolysis in pancreatic cancer." (PMID 33117704, 2020). "While the roles of SIRT2, SIRT4, and SIRT5 in pancreatic cancer progression are evident, their utility as biomarkers is not yet fully established." (PMID 39682281, 2024).
Insulin resistance (12 papers, 2014 to 2025). Increased resistance towards insulin, that is, diminished effectiveness of insulin in reducing blood glucose levels. "Previous studies have demonstrated that SIRT4 deficiency leads to accelerated insulin resistance and glucose intolerance, conditions associated with impaired wound healing." (PMID 40463174, 2025). "Due to its many different activities in inhibiting insulin secretion, Sirt4 has been linked to the emergence of T2D, which was also confirmed by studies in Sirt4 KO mice that quickly develop hyperinsulinemia, insulin resistance, and glucose intolerance." (PMID 32373514, 2020). "Recent studies have demonstrated that SIRT4 knockout (KO) mice have increased insulin secretion and ultimately glucose tolerance and insulin resistance, all of which are high-risk factors for PDAC, suggesting that SIRT4 is closely associated with PDAC." (PMID 36209169, 2023). "It has also been shown that in the early stages of diabetes mellitus type 2, SIRT4 levels may be reduced, which can result in the development of insulin resistance." (PMID 40725501, 2025). "Furthermore, SIRT4 expression is reduced in the rat model of insulin resistance and low SIRT4 mRNA expression was found in peripheral blood leukocytes in human type 2 diabetes mellitus." (PMID 25045415, 2014). "SIRT4 shows a mitochondrial localization and is a lysine deacylase that controls insulin secretion: Sirt4 KO mice progressively develop glucose intolerance and insulin resistance, highlighting the importance of this mitochondrial enzyme in regulating leucine metabolism." (PMID 36901738, 2023). "Mice lacking SIRT4 exhibit accelerated development of insulin resistance and defective adipogenesis." (PMID 40463174, 2025). "Moreover, Kristin and colleagues found that SIRT4 could control leucine metabolism through regulating the acylation levels of enzymes in the pathway, and mice lacking Sirt4 have dysregulated leucine metabolism that can lead to increased insulin and development of age-induced insulin resistance." (PMID 39372420, 2024). "Mice lacking of SIRT4 had abnormal leucine metabolism, which resulted in chronic increase of insulin secretion and accelerated senescence-induced insulin resistance." (PMID 31447696, 2019).